TNF (tumor necrosis factor)
Diseases named in the same sentence as TNF in open-access papers (continued):
Sharing a sentence is not in itself a finding about the gene and the disease.
Graves disease (18 papers, 2006 to 2025). Graves' disease is an autoimmune disorder that leads to overactivity of the thyroid gland (hyperthyroidism).It is caused by an abnormal immune system response that causes the thyroid gland to produce too much thyroid hormones. "Cytokines are elevated in autoimmune (i.e., IL-18, IL-6) and non-autoimmune hyperthyroidism (i.e., TNF-α, IL-8, IL-6), and this could be associated with the chronic effects of thyroid hormone increase." (PMID 33935970, 2021). "Furthermore, a study involving 22 SNPs in Caucasian patients with Graves’ disease (GD) showed significant association of TNF-α −238G/A and −308G/A polymorphisms." (PMID 23284977, 2012). "JWXYS may intervene in inflammation, immunity, apoptosis and other mechanisms to treat Graves’ disease through IL-17 signaling pathway, TNF signaling pathway, cytokine - cytokine receptor interaction and other signaling pathways." (PMID 37780612, 2023). "Anti-TNF therapy reduces free T4 concentrations in Graves' disease patients." (PMID 34567510, 2021). "IL-6 and TNFα are both increased in Grave's disease (hyperthyroid state), however since these cytokines have been reported to decrease adiponectin and increase C3, this cannot explain the demonstrated increase in adiponectin and decrease in C3 in the hyperthyroid state in the present study." (PMID 16472384, 2006). "COL13A1 expression in Graves’ disease and goiter thyroid samples was compared with TGF-β1 and TNF, and these were also studied in human thyroid epithelial cells and fibroblasts." (PMID 38564194, 2024).
hemorrhagic fever (18 papers, 2009 to 2025). An infectious disease caused by certain viruses or bacteria that can damage the walls of tiny blood vessels, making them leak, and can hamper the blood's ability to clot and cause severe, life-threatening illness. "Hemorrhagic fever severity is associated with hemophagocytosis, the result of TNF-α production, which promotes macrophage activation." (PMID 36788994, 2023). "In contrast, IFN-ɣ, IFN-α, IL-12, 1L-10, and tumor necrosis factor (TNF)-α were associated with death from hemorrhagic fever." (PMID 33477334, 2021). "Elevated TNFα is found in a number of other hemorrhagic fevers, including infection with Hantaan virus, Ebola virus or Puumala virus." (PMID 23083136, 2012). "It is noteworthy that elevated levels of IL-6, IL-8, IL-10, G-CSF, and TNF-alpha, which were observed in MACV-infected STAT-1 knockout mice, are correlated with the severity of human Argentinean hemorrhagic fever, caused by the related Junín virus." (PMID 21672221, 2011). "Increased levels of TNF-α have also been demonstrated in studies of patients with Korean hemorrhagic fever and patients with HCPS." (PMID 21605369, 2011). "Additionally, LASV suppresses immune cells so that they do not secrete pro-inflammatory cytokines such as tumor necrosis factor (TNF)-α, IL-6, and IL-8β, contrary to what is seen in other hemorrhagic fevers." (PMID 34094756, 2021). "In addition, we measured serum levels of vasoactive IL-6 and TNF-α proteins, which have been known to play an important role in inducing hemorrhagic fever and increasing vascular leakage." (PMID 34130738, 2021). "While the upregulation of the IFN-γ can induce plasma leakage, TNF-α may indicate for the activation of vascular endothelial cell and may increase vascular permeability which lead to hemorrhagic fever." (PMID 29651328, 2018). "The dengue virus, causes hemorrhagic fever and vascular lesions in humans, produces interleukin-4 (IL-4), IL-8, IL-6, IL-10, GM- colony stimulating factor (CSF), interferon-gamma (INF-gamma) and tumor necrosis factor alpha (TNF-alpha)." (PMID 19712456, 2009). "However, pathological cytokine responses including IFNγ, IL-6, IL-10, TNFα, and IP-10, all of which are elevated in AB6 mice during fatal Ang71 infection, have been implicated in inducing vascular permeability with the onset of hemorrhagic fever after infection with the related Dengue virus (DENV)." (PMID 27463517, 2016). "Of note, as most models of haemorrhagic fever, the infection appears to primarily involve the CNS, and although there is increased mRNA expression of IL-1, 6 and 8 and TNFα, the pattern of gene expression does not suggest a cytokine storm." (PMID 34674613, 2021). "In addition, LASV subdues the cells of the immune system thus preventing their secretion of proinflammatory cytokines including tumor necrosis factor (TNF)-α, IL-6, and IL-8β, unlike the symptoms observed in other hemorrhagic fevers." (PMID 36680186, 2023).
Hyperkeratosis (18 papers, 2018 to 2025). Hyperkeratosis is a histopathological term defining a thickened stratum corneum and may be present in many different skin conditions, with many possible overlaps. "Specifically, the accumulation of keratinocytes in the ductal infundibulum causes hyperkeratosis and induces proinflammatory cytokines, including IL‐1, IL‐6 and TNF‐α, resulting in a closed or open comedones (Grade I)." (PMID 38426932, 2024). "Nicotine has been shown to induce infundibular epithelial hyperplasia and hyperkeratosis, alter the cutaneous microbiome, stimulate release of TNF by keratinocytes and T-helper 17 cells, disturb polymorphic neutrophil granulocyte chemotaxis, and immunomodulate macrophage function." (PMID 33493574, 2022). "TNF-α and IFN-γ play crucial roles in the initiation and amplification of inflammatory responses, and both can activate keratinocytes, promote the release of pro-inflammatory mediators and disrupt skin barrier function, which causes hyperplasia, erosion, and hyperkeratosis in the epidermis." (PMID 37686078, 2023). "Cumulative release at pH 7.4 and 5.8 (72 h)↓ inflammation degree and PASI, ↓ IL-17, TNF- α, TGF-β levels, ↑ IL-10 levels↓ parakeratosis, hyperkeratosis, acanthosis." (PMID 39458602, 2024). "We observed a significant increase in inflammatory factors (such as TNF-α, IL-1β, CXCL1, CXCL2, CCL4, and TLR7) and exacerbates hyperkeratosis and keratosis in STAT3 mice." (PMID 37465147, 2023). "Taken together, these results imply that EEFR can suppress the production of TNF-α, IFN-γ, IL-6, and MCP-1, and thus, inhibit epidermal hyperplasia, hyperkeratosis, and immune cell infiltration." (PMID 37047066, 2023). "Collectively, these findings suggest that EESP can suppress the production of TNF-α, IFN-γ, IL-6, and MCP-1 and consequently inhibit epidermal hyperplasia, hyperkeratosis, and immune cell infiltration, which ameliorate the skin symptoms of CD and suppress skin-thickening." (PMID 37686078, 2023). "Moreover, the lack of TNF in these animals strongly reduced and delayed the epidermal hyperkeratosis and the increased apoptosis in keratinocytes." (PMID 33238518, 2020).
lichen planus (18 papers, 2012 to 2025). A chronic, recurrent, pruritic inflammatory disorder of unknown etiology that affects the skin and mucus membranes. "Studies linking salivary TNF-α levels and oral health pointed to the possible use of this cytokine for, among other things, risk assessment for lichen planus." (PMID 33202617, 2020). "In these cases, the development of an inflammatory reaction is somewhat surprising since TNF-α is involved in the pathogenesis of lichen planus, and TNF-α inhibitors are efficacious when used to treat refractory cases." (PMID 37175894, 2023). "There are several reports on lichenoid drug eruptions following TNF-α inhibition, and only one report on a successful treatment of lichen planus with the anti-TNF-α antibody adalimumab." (PMID 34790675, 2021). "In the present case-control study, the relationship between lichen planus and the serum levels of TNF-α and TGF-β was evaluated in two matched case and control groups." (PMID 23277861, 2012). "The production or release of TNF‐α within lichen planus lesions may significantly influence the immunopathogenesis of the disease." (PMID 39742325, 2025). "Up-regulation of intercellular adhesion molecule-1 (ICAM-1) and cytokines associated with Th 1 immune response, such as interferon (IFN)-gamma, tumour necrosis factor (TNF)- alpha, interleukin (IL)-1 alpha, IL-6 and IL-8, may also play a role in the pathogenesis of lichen planus." (PMID 22980383, 2012). "In lichen planus, our findings emphasize a primarily Th1-dominant immune response characterized by robust IFN-γ and TNF-α." (PMID 41479908, 2025). "- Lichen planus is Th1-skewed, driven by IFN-γ and TNF-α, although recent evidence also highlights significant IL-23/Th17 involvement, reflecting a broader inflammatory spectrum." (PMID 41479908, 2025). "Mixed supernatant of T cells derived from the lesions of lichen planus and lupus erythematosus induced phosphorylation of RIPK3 and MLKL in keratinocytes, but the inducing effect is dependent on the presence of TNF-α and IFN-γ in supernatant." (PMID 36344541, 2022). "Thus, the overactivation of cytotoxic CD8+ cells and uninhibited production of proinflammatory cytokines such as IL‐2, TNF‐α, and IFN‐γ by CD4+ T cells play an important role in the implication of Lichen planus." (PMID 40626171, 2025). "The pathophysiologic mechanism might be the Th1 response that is elicited by the vaccines, which in turn leads to the elevation of interleukin‐2 (IL‐2), tumor necrosis factor‐α (TNF‐α), and interferon‐γ (IFN‐γ) levels, and therefore, lichen planus induction." (PMID 35140945, 2022).
macular edema (18 papers, 2012 to 2025). "Vasoactive growth factors and inflammatory cytokines, including vascular endothelial growth factor-A (VEGF) and tumor necrosis factor (TNF)-α, are upregulated in the ocular fluids in macular edema and have been implicated in disruption of the BRB." (PMID 36960343, 2023). "Among those complications, some were more likely to be associated with anti-TNFα treatment: macular edema [OR = 11.25 (2.85–43.81), p = 0.0005], cataract [OR = 11.87 (2.37–59.49), p = 0.0026], and band keratopathy [OR = 12.89 (2.05–80.90 p = 0.0064]." (PMID 35311049, 2022). "Logistic regression analysis showed G6PD, triglyceride, cholesterol, IL-8, TNF-α, and macular edema were influencing factors for T2DM with DR." (PMID 39621725, 2024). "The results showed that G6PD, triglyceride, cholesterol, IL-8, TNF-α, and macular edema were influencing factors of DR in T2DM patients." (PMID 39621725, 2024). "In particular, IL-6 inhibitors have been reserved for use in treatment-resistant macular edema unresponsive to traditional therapies such as steroids, tumor necrosis factor alpha (TNF-alpha) inhibitors, or anti-VEGF inhibitors." (PMID 36902105, 2023). "Complete or partial responses of macular edema were achieved in 21.8% of patients treated with anti-TNF alpha agents versus 35.8% of patients treated with tocilizumab." (PMID 36902105, 2023). "Overall improvement in macular edema was achieved in 46.2% of patients treated with anti-TNF alpha agents and 58.5% of patients treated with tocilizumab." (PMID 36902105, 2023). "TNF can also have a part in the pathogenesis of macular edema and some studies report good outcome with using intravitreal anti-TNF in the treatment of diabetic macular edema and neovascular age related macular degeneration." (PMID 30206553, 2018). "The inflammatory cytokines, TNF-α and IL-6, are strongly implicated in the development of non-infectious retinal inflammation and the macular oedema that often accompanies this." (PMID 35208767, 2022). "Moreover, the anti-TNF-α therapy was effective in treating macular edema with a reduction of MMT at every follow-up visit." (PMID 32069898, 2020). "Cytokine interruption (e.g., TNF-α, IL-6 blockade) is effective in relapsing non-infectious uveitis, reducing flares and macular oedema." (PMID 41394857, 2025). "TNF-α and IL-1β are the key drivers of retinal endothelial dysfunction in non-infectious uveitis, leading to macular oedema and vascular leakage." (PMID 40305201, 2025). "This is consistent with the key role of TNF-alpha in the regulation of ocular levels of different chemokines, including VEGF, TGF-beta, angiotensin II, IL-1, IL-6, and IL-8, which drive the development of macular edema and choroidal neovascularization." (PMID 32069898, 2020).
nasopharyngeal carcinoma (18 papers, 2010 to 2025). A carcinoma arising from the nasopharyngeal epithelium. "The level of serum TNF-α was positively associated with a soaring frequency of post-treatment distant metastases and bone invasion in patients with nasopharyngeal carcinoma." (PMID 37048097, 2023). "Notably, the attenuation of the senescent state in TNF‐α‐treated nasopharyngeal carcinoma cells upon silencing WTAP underscores its therapeutic potential in mitigating age‐related or stress‐induced cellular decline." (PMID 39619978, 2024). "Furthermore, a recent pan-cancer single cell analysis of immune infiltrate in different solid tumors revealed that, in nasopharyngeal cancer, MCs have a protective role and correlate with good prognosis thanks to their production of TNFα and, in particular, their high TNFα/VEGF ratio." (PMID 37376140, 2023). "But when NOLC1 expression is down-regulated under the interference of shNOLC, the expression of MDM2 proto-oncogene is inhibited while the expression of the apoptosis-related genes (such as TNF-α) were up-regulated in nasopharyngeal carcinoma (NPC) cells." (PMID 34837693, 2021). "Cytokines such as IL-6, IL-8, IP-10, TNF-α, VEGF, EGFR, and MIP-3α were found to be elevated in nasopharyngeal carcinoma." (PMID 35964134, 2022). "Here, we show that EBERs induce inflammatory response in nasopharyngeal carcinoma (NPC) cells through Toll-like receptor 3 (TLR3), mainly featured by high level of TNFα production." (PMID 26172457, 2015). "Notably, a pan-cancer analysis showed that MCs correlate with good prognosis in nasopharyngeal cancer due to high TNFα production and a favorable TNFα/VEGF ratio, whereas TNFα-negative, VEGF-producing, MCs associate with poor outcomes in lung, colon, pancreas, and kidney cancers." (PMID 41368640, 2025).
skin aging (18 papers, 2020 to 2025). The gradual irreversible changes in structure of skin that occur as a result of the passage of time.. "This study demonstrated that P. japonicum extracts and isolated compounds exert notable aging- and inflammatory-modulating effects on TNF-α-stimulated human dermal fibroblasts (an inflammatory cytokine associated with skin aging)." (PMID 41465872, 2025). "In addition to the protective effect of L3R on TNF-α-induced skin aging, there are other potential effects associated with L3R." (PMID 37507970, 2023). "UV-induced intracellular ROS and pro-inflammatory cytokines such as TNF-α are key mediators of skin aging." (PMID 40699775, 2025). "IL-6, IL-1β, TNF-α and Col-I are the important cytokines in the pathological mechanism of skin aging." (PMID 37927602, 2023). "On the other hand, the upturning effect of aging on the anti-inflammatory function of TRPV1 denoted its impaired role in the suppression of tumor necrosis factor α in old mice, and of numerous cytokines involved in skin aging." (PMID 37108704, 2023). "In conclusion, in an ongoing study focused on the discovery of potential bioactive phytochemicals, we investigated protective natural products from ginkgo fruit (G. biloba fruit) against skin aging by TNF-α stimulation." (PMID 37507970, 2023). "Accordingly, we investigated natural products with potential protective effects against TNF-α-induced skin aging." (PMID 37507970, 2023). "As part of continuing natural product discovery for bioactive phytochemicals from diverse natural resources, we investigated natural products from ginkgo fruit (G. biloba fruit) with potential protective effects against TNF-α-induced skin aging." (PMID 37507970, 2023). "Although further studies are needed, these results suggest that L3R is a potential protective agent against TNF-α-induced skin aging." (PMID 37507970, 2023). "In this study, as part of our ongoing discovery of natural products, we investigated potential natural products derived from ginkgo fruit (Ginkgo biloba fruit) with protective effects against TNF-α-induced skin aging." (PMID 37507970, 2023). "The major contributor to skin aging is UV radiation, which activates pro-inflammatory cytokines including TNF-α." (PMID 36501357, 2022). "We evaluated the protective effects of the extract and the compounds isolated from P. chinensis on TNF-α-stimulated skin aging in HDFs." (PMID 36501357, 2022). "Extrinsic or intrinsic skin aging produces an excess of skin destructive factors such as tumor necrosis factor (TNF)-α, which is a major mediator of the aging process." (PMID 36421436, 2022). "The mechanism by which compound 1 inhibits TNF-α-stimulated skin aging in HDFs involves the inhibition of NF-κB, AP-1, and MAPKs activation." (PMID 33573167, 2021). "An increase in pro-inflammatory cytokines, such as IL-1, IL-6 and TNF-α, is generally observed with skin aging." (PMID 34573004, 2021). "However, most research to date has focused on UV-induced skin aging and the TNF-α-induced skin-aging process, and its inhibitors are relatively underexplored." (PMID 40364386, 2025). "However, treatment with compounds 1 and 3 significantly restored procollagen secretion, suggesting their potential roles in promoting collagen synthesis and counteracting TNF-α-induced skin aging." (PMID 41465872, 2025). "Therefore, we investigated potential natural products with protective effects against TNF-α-induced skin aging from G. biloba fruit." (PMID 37507970, 2023). "Thus, several assays should be conducted to identify the signaling pathway for the ROS-related downregulation of L3R in TNF-α-induced skin aging." (PMID 37507970, 2023). "Thus, the inhibition of TNF-α-induced ROS generation is a crucial element in preventing skin aging and related diseases." (PMID 36501357, 2022). "Subsequently, we investigated whether the extract could prevent skin aging in TNF-a-stimulated HDFs." (PMID 36290617, 2022).
skin aging (continued). "Thus, the inhibition of TNF-α and ROS is the key to preventing skin aging." (PMID 37891882, 2023). "Consequently, the inhibition of ROS production and TNF-α is the key to preventing skin aging." (PMID 36499128, 2022). "Given that SOD3 reduces collagen degradation and increases collagen production in fibroblasts under 3D culture conditions in the absence and presence of TNF-α, we propose that SOD3 has an effect of delaying both intrinsic and extrinsic skin aging." (PMID 35624792, 2022). "Therefore, we investigated whether GDHBA could prevent skin aging in TNF-α-stimulated HDFs." (PMID 36499128, 2022). "In our previous study, we examined plant-derived agents that could prevent skin aging and found that hot water extract from Morus alba fruits significantly inhibited MMP-1 secretion in TNF-α-stimulated HDFs." (PMID 36499128, 2022). "In addition, TNF-α activates the mitogen-activated protein kinase (MAPK) pathway through phosphorylation, leading to increased MMP expression, accelerated collagen breakdown, and progression of skin aging." (PMID 41465872, 2025).